TPP1 (tripeptidyl peptidase 1)
Diseases named in the same sentence as TPP1 in open-access papers (continued):
Sharing a sentence is not in itself a finding about the gene and the disease.
neurodevelopmental disorder (1 paper, 2020). A behavioral and cognitive disorder with onset during the developmental period that involves impaired or aberrant development of intellectual, motor, or social functions. "Similarly, the diagnostic rate for TPP1 in the general population of children with neurodevelopmental disorders was found to be 1.4%, whereas it resulted 4.7% in our study." (PMID 32631363, 2020).
TPP1 also shares sentences with these, for which no sentence is quoted: Seizure (8 papers); Cerebellar atrophy (7); Dystonia (6); Tremor (5); metabolic disease (4); movement disorder (4); behavioural disorders (3); cerebellar ataxia (3); Cerebral atrophy (3); Chorea (3); dementia (3); genetic disease (3); idiopathic pulmonary fibrosis (3); myoclonic epilepsy (3); Myoclonus (3); Parkinsonism (3); retinal disease (3); breast carcinoma (2); Choreoathetosis (2); chronic obstructive pulmonary disease (2); cone-rod dystrophy (2); COVID-19 (2); developmental delay (2); Duchenne muscular dystrophy (2); epilepsy syndrome (2); epileptic encephalopathies (2); Fabry disease (2); Gaucher disease (2); Hunter syndrome (2); language delay (2).
A further 83 diseases each share a sentence with TPP1 in 2 papers or fewer.